IL2 (interleukin 2)
Diseases named in the same sentence as IL2 in open-access papers (continued):
Sharing a sentence is not in itself a finding about the gene and the disease.
pneumonitis (4 papers, 2019 to 2024). An inflammatory process affecting the lung parenchyma. "Earlier studies showed that IL-2 administration can cause durable antitumor activity but also increase the frequency of circulating regulatory T cells and can induce severe side effects such as pneumonitis." (PMID 33807011, 2021). "The toxicities were generally manageable and consistent with expectations from HD IL-2 but physicians should watch for immune related toxicities such as pneumonitis." (PMID 30777131, 2019). "One patient who had received prior PD-L1 blockade developed drug induced pneumonitis with HD IL-2 requiring steroid therapy." (PMID 30777131, 2019). "However, there was a case report of a patient with presumed IL-2 induced pneumonitis that required steroid therapy." (PMID 30777131, 2019). "However, one of the institutions reported a patient with presumed, severe pneumonitis during HD IL-2 therapy that was felt to be related to prior PD-L1 inhibition." (PMID 30777131, 2019). "Initial imaging was consistent with pulmonary edema from HD IL-2 induced capillary leak, however his condition did not improve with diuresis and repeat imaging showed worsening pulmonary infiltrates suggestive of pneumonitis." (PMID 30777131, 2019). "Pneumonitis during HD IL-2 has not been previously reported." (PMID 30777131, 2019). "In a case of indolent pneumonitis where there are already immune infiltrates within the lung, it is possible that there may be a recall exacerbation when anti-PD1 therapy is followed by HD IL-2." (PMID 30777131, 2019).
psoriasis vulgaris (4 papers, 2018 to 2024). Plaque psoriasis is the most common presentation of psoriasis. "In this study, the cross-sectional study identified the fact that serum CRP, IL-2, IL-6, TNF-α and IFN-γ levels were significantly increased in PsA patients, and positive serum CRP, IL-6 and TNF-α were independently associated with PsA among psoriasis vulgaris patients." (PMID 39335643, 2024).
relapsing-remitting MS (4 papers, 2016 to 2024). "We showed that IL-2 levels in the cerebrospinal fluid of patients with newly diagnosed relapsing-remitting multiple sclerosis (RRMS) were significantly higher than those of healthy controls." (PMID 39000506, 2024). "In short, we expanded whole peripheral blood mononuclear cells (PBMCs) from untreated relapsing-remitting MS (RRMS) patients (nRRMS = 19), NAT-treated RRMS patients (nNAT = 10), and healthy donors (nHD = 16) by addition of R848 at 2.5μg/ml and IL-2 at 1’000 IU/ml." (PMID 39257578, 2024).
sclerosing cholangitis (4 papers, 2021 to 2025). A chronic, autoimmune inflammatory liver disorder characterized by narrowing and scarring of the lumen of the bile ducts. "Additionally, IL-2 and IL-2 immune complexes promote the expression of CD39 on hepatic Tregs, which inhibits the proliferation of CD8+ T cells and reduces the expression of osteopontin and TNF-α to diminish biliary fibrosis in murine sclerosing cholangitis." (PMID 33869241, 2021).
Skin rash (4 papers, 2014 to 2023). A red eruption of the skin. "These in vivo observations suggest that severe skin rash observed in clinical situations is driven by enhanced IL-2 secretion via STK-10 “off-target” inhibition." (PMID 30868372, 2019). "Grade 3–4 toxicity of gefitinib was represented by skin rash (7%), asthenia/anorexia (6%) and diarrhea (7%); patients treated with IL-2 showed grade 2–3 fever (46%), fatigue (21%) and arthralgia (13%)." (PMID 25271833, 2014). "IL-2 is a proinflammatory cytokine and its enhanced secretion may be a putative mechanism for severe skin rash." (PMID 30868372, 2019).
small cell lung carcinoma (4 papers, 1996 to 2025). Small cell lung cancer (SCLC) is a highly aggressive malignant neoplasm, accounting for 10-15% of lung cancer cases, characterized byrapid growth, and early metastasis. "In the present study, we assessed the effects of transfecting NCI-H446 small cell lung cancer cells with genes encoding three IL-15 variants: prototypical IL-15, mature IL-15 peptide, and modified IL-15 in which the IL-2 signal peptide is substituted for the native signal peptide." (PMID 29296227, 2017). "Consistent with that idea, we found that modifying IL-15 with the IL-2 signal peptide enhanced IL-15 secretion as well as its ability to induce cell cycle arrest in NCI-H446 small cell lung cancer cells and increase NK cell antitumor activity." (PMID 29296227, 2017). "CD39 expression on secreting CD4 Tregs was related to an increased risk of small-cell lung cancer (SCLC) (OR, 1.0306 [95% CI, 1.0006–1.0616]), mediated by interleukin (IL)-2 and IL-6 with mediation proportions of 8.43% (95% CI, 0.00005−0.005) and 5.1% (95% CI, 0.00006–0.003), respectively." (PMID 41292522, 2025).
Takayasu arteritis (4 papers, 2016 to 2025). A rare inflammatory large-vessel vasculitis primarily affecting the aorta and its major branches, but also other large vessels, causing stenosis, occlusion, or aneurysm. "Furthermore, visualization of Takayasu arteritis has been reported in a case study utilizing [99mTc]IL-2 scintigraphy, pointing toward the possible utility of IL-2 based lymphocyte targeted imaging in the detection of GCA." (PMID 35733858, 2022).
teratocarcinoma (4 papers, 2018 to 2024). A germ cell tumor characterized by the presence of an embryonal carcinoma component and a teratoma component. "NeoTM-L19 is not glycosylated and we were pleased to see how the L19-based targeted delivery of the engineered IL2 and IL15 mimic led to an improved therapeutic effect for the F9 teratocarcinoma model." (PMID 33216834, 2020).
uveal melanoma (4 papers, 2002 to 2024). A melanoma derived from melanocytes of the uveal tract. "Interestingly, abnormally elevated levels of many cytokines, including IL-2, IL-4, IL-6 and IL-8, have been observed in the vitreous of eyes from patients with uveal melanoma." (PMID 35163491, 2022). "Recent reports on the therapeutic efficacy of IL-2 in combination with histamine in hepatic metastasis of uveal melanoma invigorate the hope that immune modulation may serve as a new tool to treat this disease." (PMID 12373596, 2002).
abscesses (3 papers, 2010 to 2025). "Initial studies have shown that protection from abscess formation was mediated by IL-2 because abscesses were prevalent in mice treated with anti-IL-2 antibodies and ZPS." (PMID 21234388, 2010). "High levels of IL‐2 observed after drug treatment can prevent the recurrence of abscesses." (PMID 40453734, 2025). "IL‐2 plays a protective role in the development of various types of abscesses." (PMID 40453734, 2025). "Furthermore, the adoptive transfer of CD4 T cells from mice that were vaccinated with ZPS prevented the induction of intra-abdominal abscesses in the recipients in an IL-2-dependent manner." (PMID 21234388, 2010).
acute leukemia (3 papers, 2010 to 2021). A clonal (malignant) hematopoietic disorder with an acute onset, affecting the bone marrow and the peripheral blood. "In a prospective analysis, 105 patients with standard-risk acute leukemia (AML, ALL or MDS) were MRD positive after allo-SCT—of which, 49 received low-dose IL-2 only, and 56 modified DLI, with or without low-dose IL-2." (PMID 31878060, 2019).
acute T cell leukemia (3 papers, 2015 to 2021). "Cho etal. also reported that PYC inhibited expression of IL-1β mRNA in RAW264.7 cells and IL-2 expression in JurlatE6.1 cells, a human acute T-cell leukemia cell line, through different mechanisms." (PMID 26367267, 2015). "HSH2D inhibits the transcriptional activation of the IL-2 promoter, specifically at the RE/AP element of IL-2, which is regulated by CD28, and HSH2D expression contributes to methotrexate resistance in human T-cell acute lymphoblastic leukemia." (PMID 34512722, 2021). "Jurkat cells are T cells lymphoblasts, from acute T cell leukemia, which have been used to elucidate the mechanisms behind the TCR signaling and interleukin production, such as IL-2." (PMID 32708342, 2020).
adenoma (3 papers, 2010 to 2023). A neoplasm arising from the epithelium. "Decreased IL-2 concentration during the trial increased the risk of any adenoma recurrence (4th vs 1st quartile, OR=1.68, 95% CI=1.13–2.49), whereas decreased IL-1β or IL-10 reduced the risk of advanced adenoma recurrence (OR=0.37, 95% CI=0.15–0.94; OR=0.39, 95% CI=0.15–0.98, respectively)." (PMID 20924374, 2010). "Furthermore, cytokines that are known to promote (IL-12, IFN-γ, and IL-2) or regulate (IL-10, IL-4, and IL-17) T-cell polarization and differentiation were similar in the serum of individuals with and without detectable adenomas." (PMID 25884547, 2015). "Although we did not observe significant alterations in serum cytokine levels in study participants with adenomas relative to controls, we did observe an overall decrease in the serum levels of IL-2, IL-12p70, and IFN-γ in participants with adenomas as compared to those without an adenoma." (PMID 25884547, 2015).
adenovirus infection (3 papers, 2008 to 2021).
alcohol (3 papers, 2016 to 2025). "Chronic alcohol use inhibits B cell responsiveness to cytokines such as IL-2 and IL-4, which are critical for B cell differentiation and antibody production." (PMID 40181820, 2025).
Ascites (3 papers, 2010 to 2021). Accumulation of fluid in the peritoneal cavity (between the layers of the peritoneum that lines the abdomen). "EOC-associated ascites had a significantly (p < 0.0001) higher proportion of NK CD56bright lymphocytes than blood, which, in addition, were more responsive (p < 0.05) to stimulation by IL-2 than CD56dim NK." (PMID 34359872, 2021).
autoimmune gastritis (3 papers, 2012 to 2025). Inflammation of the body fundic mucosa of the stomach. "For example, neutralization of circulating IL-2 with an anti–IL-2 monoclonal antibody for a limited period induces autoimmune gastritis in BALB/c mice." (PMID 41383600, 2025).
benign prostatic hyperplasia (3 papers, 2011 to 2023). A non-cancerous nodular enlargement of the prostate gland. "We evaluated local IL-2, IL-7, IL-15 and IL-21 gene expression in prostate tissues from patients with early stage PCA or benign prostatic hyperplasia (BPH)." (PMID 21943235, 2011).
breast adenocarcinoma (3 papers, 2007 to 2020). "We used a multivariate principal component analysis applied to analyze the joint behavior of serum concentrations of IFN-γ, IL-2, IL-10 and IL-4, during the different phases of tumor immunoediting, in CBi/L mice challenged with M-406 mammary adenocarcinoma." (PMID 33312693, 2020). "In that study, PyMT and Neu murine tumour cells derived from breast adenocarcinoma cells and transduced with Adenovirus-type 5 vectors produced 788 and 1204 ng 106 cells−1 24 h−1, respectively, of IL-12, and 32 and 51 ng 106 cells−1 24 h−1 of IL-2." (PMID 17595664, 2007).
bullous pemphigoid (3 papers, 2017 to 2024). Bullous pemphigoid (BP) is the most common form of autoimmune bullous dermatosis. "This study aimed to evaluate the efficacy of low-dose interleukin (IL-2) treatment for bullous pemphigoid (BP) caused by anti-programmed cell death protein 1/ligand 1 (PD-1/PD-L1) inhibitors." (PMID 39720733, 2024). "Elevated levels of interleukin-2 (IL-2), interleukin-8 (IL-8), growth factor insulin (IGF-1), transforming growth factor (TGF- β) and bone marrow factor - 4 (BMP-4) were found in corneas with bullous keratopathy." (PMID 29450379, 2017).
cardiac hypertrophy (3 papers, 2021 to 2024). "Qiagen Ingenuity Pathway Analysis (IPA) highlighted 118 canonical pathways that were significantly modulated by vagal activity, of which 14 had a z score of ≥2/≤−2, including EIF-2, IL-2, integrin, and NFAT-regulated cardiac hypertrophy." (PMID 38047311, 2024). "The most significantly affected signaling pathways were EIF-2, IL-2, integrin, NGF, VEGF, estrogen receptor, IL-7, FLT3, FGF, oxytocin, cardiac hypertrophy, role of NFAT in cardiac hypertrophy, and neutrophil extracellular trap pathways." (PMID 38047311, 2024).
cerebral malaria (3 papers, 2014 to 2024). A sequestration of Plasmodium falciparum in the brain, which can cause coma and/or seizures. "In the case of experimental cerebral malaria, the authors found a higher mRNA expression of the pro-inflammatory cytokines IL-2, IL-6, IL-10, IL-17, IFN-γ, and TNF in the serum, hippocampus, and frontal cortex in mice infected with Plasmodium berghei." (PMID 39057789, 2024).
cervical intraepithelial neoplasia (3 papers, 2014 to 2023). "Few studies examined the associations between IL-2 and high-risk human papillomavirus (HPV) with risk of cervical intraepithelial neoplasia (CIN)." (PMID 37256111, 2023).
Chronic colitis (3 papers, 2015 to 2023). A chronic inflammatory disease of the large intestine (colon, cecum and rectum). "Many researchers have reported that excessive Th1 cells in intestinal mucosa are the main reason for chronic colitis; these cells produce interferon (IFN)-γ and interleukin-2 (IL-2)." (PMID 25889203, 2015).
coagulation disorders (3 papers, 2014 to 2022). "Most biomarkers are related to the immune system (SAA,TNF-∝, and IP-10) or coagulopathies (D-dimer, antithrombin, and VWF) and a few have already been established as cancer biomarkers (ACE2, IL-6, IL-4 and IL-2)." (PMID 32935101, 2020).
common variable immunodeficiency (3 papers, 2015 to 2019). "Low dose Ig or IRT has also been shown to decrease production of pro-inflammatory cytokines such as IL-2, IL-12, and TNF-α by monocytes in common variable immunodeficiency (CVID) patients." (PMID 31613907, 2019).
cystic fibrosis (3 papers, 2015 to 2020). Autosomal recessive disorder caused by pathogenic variants in the CFTR gene (cystic fibrosis transmembrane conductance regulator), which encodes a chloride and bicarbonate channel expressed in epithelial cells, and follow the diagnosis criteria. "Dysregulation of IL-2 levels in T lymphocytes was also observed in patients with cystic fibrosis, suggesting that this cytokine plays a role in fibrotic processes." (PMID 33047019, 2020). "Comparison of cytokine expression and phenotypic markers revealed increased proportions of CD40L positive T-cells that lack Interleukin-2 expression as a marker for chronic Mycobacterium abscessus infections in cystic fibrosis patients." (PMID 25742660, 2015).
deep vein thrombosis (3 papers, 2020 to 2025). "According to a previous study on deep vein thrombosis, platelet activation is involved in endothelial cells and serum inflammatory factors, with the regulation of p-selectin, GPIIb/IIIa, IL-2, IL-6, and IL-8." (PMID 36851332, 2023). "Furthermore, previous research indicates that the occurrence of thrombosis increased number of Tregs, which consistent with our findings that Cluster 3 has the highest number of thrombotic events and also shows an increased numbers of Tregs and IL‐2 producing CD4+ T cells." (PMID 39965097, 2025).
demyelination (3 papers, 2011 to 2023). "Overall, our results suggest that IL-6, IL-10 or TGF-β are not required for TH17 cell induced demyelination and expression of IL-2 by HSV-IL-2 plays an important role in the generation of pathogenic TH17 cells as was reported previously." (PMID 36817487, 2023). "To assess the possible involvement of host IL-2 in the HSV-IL-2-induced demyelination, we used BALB/c-STAT4−/− mice, which do not mount a TH1 response, and BALB/c-STAT6−/− mice, which do not mount a TH2 response." (PMID 21364747, 2011).
diabetic retinopathy (3 papers, 2012 to 2025). "The ability of low-dose IL-2 to increase Tregs in blood, spleen and retina of diabetic mice emphasises the utility of this approach to influence Tregs in diabetic retinopathy." (PMID 40133487, 2025). "Our studies are focused on IL-2 as a potential therapeutic for diabetic retinopathy, as this cytokine binds with high affinity to the heterotrimeric IL-2 receptor, including the alpha subunit (CD25) on T cells and immune cells such as natural killer cells (NK cells)." (PMID 40133487, 2025). "Here, we used a mouse model of streptozocin-induced diabetic retinopathy to determine whether low-dose IL-2 increased the abundance and functionality of Tregs, as well as the Treg:CD8+ T cell ratio, in blood and lymphoid tissues." (PMID 40133487, 2025). "The effect of low-dose IL-2 treatment has yet to be evaluated in diabetic retinopathy." (PMID 40133487, 2025). "We found that low-dose IL-2 restored the number of TIGIT+ Tregs in diabetic retinopathy." (PMID 40133487, 2025). "However, IL-2 levels in the vitreous humour have been reported to be increased in individuals with diabetic retinopathy, although the study size was limited in this study." (PMID 40133487, 2025). "Our finding that low-dose IL-2 increased the Treg:CD8+ T cell ratio in the blood and spleen of OIR mice and mice with diabetic retinopathy indicates an interaction between these cell populations." (PMID 40133487, 2025). "Here, we report that low-dose IL-2 therapy increased Tregs and reduced CD8+ T cells in the retinas of OIR and diabetic retinopathy mouse models." (PMID 40133487, 2025). "In another study aiming at the treatment of diabetic retinopathy, Zeng and collaborators (2019) developed PLGA/chitosan nanoparticles containing interleukin-2, a cytokine with anti-angiogenic and antitumor efficacy." (PMID 35890326, 2022). "In conclusion, we demonstrate that Tregs and CD8+ T cells penetrate retinal tissue in diabetic retinopathy, and low-dose IL-2 increases the Treg:CD8+ T cell ratio and ameliorates vascular damage, indicating its potential as a treatment for diabetic retinopathy." (PMID 40133487, 2025). "We aimed to determine whether treatment with low-dose IL-2 expands and activates Tregs and reduces CD8+ T cells in the retina, and attenuates retinal inflammation and vasculopathy in murine models of diabetic retinopathy and neovascular retinopathy." (PMID 40133487, 2025). "It will be important in future clinical research to determine whether low-dose IL-2 increases the ocular levels of IL-2 in those with diabetic retinopathy, although there was no detrimental effect on the mouse retina." (PMID 40133487, 2025). "Although diabetic retinopathy was not studied, the findings in OIR mice demonstrate that high-dose IL-2, but not low-dose IL-2, increased NK cells in blood compared with OIR controls, and CD8+ T cells in blood and NKT cells in pooled lymph nodes compared with room air controls." (PMID 40133487, 2025).
Disseminated intravascular coagulation (3 papers, 2022 to 2025). Disseminated intravascular coagulation is characterized by the widespread activation of coagulation, which results in the intravascular formation of fibrin and ultimately thrombotic occlusion of small and midsize vessels. "Interestingly, BrHPP and IL-2, followed by either no additional treatment or Vδ2-enriched autologous PBMC adoptive cell therapy with low-dose IL-2 as an adjunct only caused adverse effects, such as disseminated intravascular coagulation or tachyphylaxis with repeated dosing." (PMID 40148988, 2025). "Biopsies obtained at the end of the study period did not demonstrate evidence of hyperacute rejection, disseminated intravascular coagulation (DIC), hyperinflammation, excessive cytokine release (IL-2, IL-6, IL-10, IL-13), or complement dysregulation." (PMID 38020483, 2023).